RN7SKP87 (RN7SK pseudogene 87)
Gene: Miscellaneous RNA gene on chromosome 9 (100,581,079 to 100,581,379, reverse strand). Ensembl gene ENSG00000200966.
Homologues: Orthologues: chimpanzee 7SK (96% identical), mouse Gm54931 (67% identical). Paralogues in human: RN7SKP176 (78% identical), 7SK (77% identical), RN7SKP203 (77% identical), RN7SKP180 (77% identical), RN7SKP255 (77% identical), RN7SKP294 (77% identical), RN7SKP9 (77% identical), RN7SKP71 (76% identical), RN7SKP150 (76% identical), RN7SKP25 (76% identical), RN7SKP204 (75% identical), RN7SKP75 (75% identical), and 283 more.